HNRNPC (heterogeneous nuclear ribonucleoprotein C)
Diseases named in the same sentence as HNRNPC in open-access papers (continued):
Sharing a sentence is not in itself a finding about the gene and the disease.
glioma (18 papers, 2019 to 2025). A benign or malignant brain and spinal cord tumor that arises from glial cells (astrocytes, oligodendrocytes, ependymal cells). "Herein, we found that HNRNPC mRNA and protein overexpression were associated with a poor prognosis for patients with gliomas, based on the data from TCGA, the CGGA, and the TMAs." (PMID 38830885, 2024). "Defined prognostic risk signature: HNRNPC, ZC3H13, and YTHDF2.HNRNPC plays an important role in malignancy and contributes to the development of gliomas.High expression of HNRNPC correlates with a favourable prognosis." (PMID 36831575, 2023). "Moreover, we used western blot, RT-PCR, and immunohistochemical staining to verify the expression of HNRNPC was associated with malignancy and development of gliomas." (PMID 33134160, 2020). "Overall, these results highlight HNRNPC as a widely active epitranscriptomic regulator in the glioma microenvironment, suggesting a potential pan-lineage regulatory role, while other markers appear more context- or cell-type specific." (PMID 40565233, 2025). "With respect to m6A readers, according to a Lasso-Cox regression algorithm, glioma patients with high expression of HNRNPC had a good prognosis." (PMID 40469294, 2025). "In multiple tumor types, notably BRCA, HNSC, and glioma, HNRNPC emerged as the most broadly and abundantly expressed regulator across malignant and immune cells, consistent with its known role in m6A-mediated alternative splicing and RNA maturation." (PMID 40565233, 2025). "In conclusion, among the currently known m6A readers, although highly expressed HNRNPC is a protective factor for glioma, high HNRNPC expression of other readers always indicates a poor prognosis in glioma patients." (PMID 40469294, 2025). "To explore the biological function of HNRNPC in gliomas, we examined the effects of knocking down or overexpressing HNRNPC on the proliferation, migration, and invasion of glioma cells." (PMID 38830885, 2024). "Abnormal HNRNPC expression is closely related to the occurrence and development of various tumors, but the role of HNRNPC-mediated m6A modifications in gliomas and the mechanism whereby HNRNPC functions as an m6A reader are still largely unclear." (PMID 38830885, 2024). "HNRNPC overexpression has been reported in gliomas; however, its function as an m6A reader remains limited." (PMID 38830885, 2024). "Kaplan–Meier analysis indicated that high HNRNPC expression was correlated with poor overall survival (OS) in patients with glioma." (PMID 38830885, 2024). "We analyzed differential MeRIP-seq peaks and RNA-seq-based differentially expressed genes in HNRNPC-knockdown glioma cells to identify the direct targets of HNRNPC." (PMID 38830885, 2024). "Biologically, HNRNPC knockdown markedly repressed malignant phenotypes of glioma in vitro and in vivo, whereas ectopic HNRNPC expression had the opposite effect." (PMID 38830885, 2024). "Previous studies have shown that YTHDF1, YTHDF2, IMP2 and hnRNPA2B1 are highly expressed in gliomas, while hnRNPC is poorly expressed in gliomas." (PMID 35688823, 2022). "We also discovered that the SFs NOVA1, HNRNPC, HNRNPLL, and RBM4 are independent risk factors that affect the prognosis and immune cell infiltration of patients with glioma." (PMID 35832652, 2022). "Generally, nuclear-localized lncRNAs regulate genes via interactions with proteins, e.g., the lncRNA DDX11 antisense RNA 1 aggravates glioma cell malignancy by targeting HNRNPC." (PMID 37303942, 2021). "With the increase in HNRNPC expression, the malignancy of glioma showed an increasing tendency (p < 0.01)." (PMID 33134160, 2020). "We demonstrated that the expression level of HNRNPC significantly contributed to malignant progression of glioma." (PMID 33134160, 2020). "Similarly, in HNSC and glioma, HNRNPC was strongly expressed in monocytes/macrophages and T-cell subsets, indicating a pan-lineage regulatory function possibly supporting immune suppression or evasion mechanisms." (PMID 40565233, 2025).
glioma (continued). "Moreover, the inhibition of hnRNPC can reduce the expression of miRNA-21 in gliomas and promote the expression of PDCD4, thus inhibiting metastasis." (PMID 40469294, 2025). "In this study, public-database analysis and IHC analysis of TMAs revealed that HNRNPC was highly expressed in gliomas, that its expression correlated positively with the degree of tumor malignancy, and that high HNRNPC expression in patients also correlated with poor survival." (PMID 38830885, 2024). "Moreover, in agreement with TCGA and Chinese Glioma Genome Atlas (CGGA) data, the IHC results of the TMA HBraG155Su01 revealed that patients with glioma and high HNRNPC expression had a worse OS." (PMID 38830885, 2024). "A previous study analyzed the differential expression of m6A modification-related genes in glioma and normal tissue by bioinformatics, result found that HNRNPC was overexpressed in multiple glioma data sets, and its expression was positively correlated with the degree of tumor malignancy." (PMID 38830885, 2024). "To access the potential function of HNRNPC in gliomas, we analyzed RNA-sequencing (RNA-seq) data from The Cancer Genome Atlas (TCGA) glioma datasets and found that HNRNPC was expressed at significantly higher levels in gliomas than in normal tissues." (PMID 38830885, 2024). "To determine whether HNRNPC depletion suppressed glioma tumor growth in vivo, we established stable U87 cell lines by integrating an HNRNPC-knockdown (HNRNPC-KD) vector or the control vector." (PMID 38830885, 2024). "Moreover, HNRNPC overexpression was required for glioma cell proliferation, migration, and invasion in vitro and in vivo." (PMID 38830885, 2024). "Correlation between HNRNPC expression and clinicopathological features of glioma patients." (PMID 33134160, 2020). "As is visible in the violin plot, the mRNA expression levels of YTHDF2, YTHDF1, METTL3, RBM15 and HNRNPC were up‐regulated in glioma compared to normal tissues, whereas the expression levels of ALKBH5, WTAP, YTHDC2, ZC3H13 and METTL14, especially of FTO, were decreased in glioma." (PMID 32449290, 2020). "In addition, a prognostic model was constructed using the three genes (ZC3H13, HNRNPC, and YTHDF2) identified by LASSO regression, which stratified the OS of patients with gliomas into high- and low-risk groups." (PMID 33134160, 2020). "We also observed the OS in the glioma which showed that the high expression of HNRNPC might have a good prognosis by Kaplan–Meier method." (PMID 33134160, 2020). "Thus, we used 25 different grade of glioma tissues that were evaluated immunohistochemically to further study the relationship between the expression of HNRNPC and gliomas in depth." (PMID 33134160, 2020). "In addition, multivariate analysis revealed that HNRNPC overexpression was a significant independent prognostic indicator for OS in glioma (hazard ratio = 2.260, 95% confidence interval = 1.259–4.060, p = 0.0063) after adjusting for age, gender and the tumor grade." (PMID 38830885, 2024). "DDX11-AS1 interacts with hnRNPC and thus activates the Wnt/β-catenin and AKT pathways, which promote the EMT process in gliomas." (PMID 40469294, 2025). "The protein level of IRAK1 was decreased in HNRNPC-knockdown glioma cells, whereas IRAK1 protein was increased after overexpressing HNRNPC." (PMID 38830885, 2024). "We demonstrated the role of HNRNPC in tumorigenesis and its function in regulating IRAK1 mRNA stability in an m6A-dependent manner, which was necessary for the malignant behavior of glioma cells by resulting in activation of the MAPK signaling pathway." (PMID 38830885, 2024). "We demonstrated that NOVA1, HNRNPC, HNRNPLL, and RBM4 were independent prognostic factors for glioma, and their expression was verified by western blotting analysis." (PMID 35832652, 2022). "Our study found that genes involved in AS events affected glioma survival including NOVA1, HNRNPC, HNRNPLL, RBM4." (PMID 35832652, 2022).
glioma (continued). "For the m6A methylation readers, the expression of HNRNPC, YTHDF1, and YTHDF2 was significantly increased in high-grade gliomas." (PMID 30810537, 2019). "However, the function and mechanism of heterogeneous nuclear ribonucleoprotein C (HNRNPC), an RNA-binding protein and m6A reader in gliomas remains to be comprehensively and extensively explored." (PMID 38830885, 2024). "To investigate whether IRAK1 is responsible for HNRNPC function during glioma tumorigenesis, we knocked down IRAK1 in a background of ectopic HNRNPC expression." (PMID 38830885, 2024). "Twenty-two vital RBPs, IGF2BP1, IGF2BP3, EIF4A3, hnRNPC, and AGO2, can bind to circRNAs and may play important biological functions in glioma." (PMID 33323543, 2020).
lung carcinoma (18 papers, 2015 to 2025). "Our analysis revealed that HNRNPC is overexpressed in a wide range of common malignancies, including liver and lung cancers, and is strongly linked to unfavorable outcomes." (PMID 39735682, 2025). "Kaplan-Meier survival analysis showed that higher expression levels of both KHSRP and HNRNPC were strongly associated with a shorter survival time for lung cancer patients." (PMID 31775888, 2019). "Kaplan-Meier survival analysis showed that high expression of HNRNPC was strongly associated with a short survival time for lung cancer patients." (PMID 31775888, 2019). "HNRNPC overexpression significantly promotes lung cancer cell proliferation, migration, and invasion in vitro and in vivo." (PMID 41154660, 2025). "A similar approach has been successfully used to uncover the contribution of hnRNPC to chemotherapy resistance in lung cancer." (PMID 37298909, 2023). "Previous studies have shown that HNRNPC is highly expressed in lung cancer, gastric cancer, ovarian cancer, and other tumor cells." (PMID 34966539, 2021). "In NSCLC cell lines, overexpression of HNRNPC significantly promoted lung cancer cell proliferation, migration, and invasion in vitro and in vivo." (PMID 31775888, 2019). "In this support, interaction of hnRNPK, hnRNPC, hnRNPL and hnRNPA2/B1 with hnRNPD in cervical and lung cancer cells has been reported earlier." (PMID 26318153, 2015). "Importantly, KHSRP protein expression was positively correlated with that of HNRNPC, suggesting a potential KHSRP-HNRNPC pathway in lung cancer tissues (R = 0.481, P < 0.01)." (PMID 31775888, 2019). "The results indicated that KHSRP could interact with HNRNPC and HNRNPC may promote the metastasis of lung cancer through IFN-α-JAK-p-STAT1 signaling pathway." (PMID 31775888, 2019). "HNRNPC overexpression was observed in a variety of human cancers, including lung cancer HNRNPC, as a protein-coding gene, could also interact with KHSRP to activate the IFN-α-JAK-p-STAT1 signaling pathway and promoted NSCLC cell proliferation, migration, and invasion." (PMID 34179079, 2021). "However, the exact function and molecular mechanism of HNRNPC in lung cancer are still unclear." (PMID 31775888, 2019). "The results showed that the expression profiles of eight m6A regulators (ALKBH5, FTO, HNRNPC, METTL14, RBM15, YTHDC1, YTHDC2, and ZC3H13) were significantly different among the three different lung cancer subtypes (P < 0.01)." (PMID 34805165, 2021). "To evaluate the expression profile of m6A readers in lung cancer, we analyzed known readers, including YTHDF1/2/3, YTHDC1/2, HNRNPA2B1, HNRNPC/G, eIF3A, FMR1 and IGF2BP1/2, in LUAD and lung squamous cell carcinoma (LUSC) via the GEPIA database." (PMID 33232910, 2021). "In this study, we demonstrated that KHSRP colocalized and coimmunoprecipitated with HNRNPC in lung cancer cells, suggesting that KHSRP can specifically interact with HNRNPC to form a complex in the nuclei of NSCLC cells." (PMID 31775888, 2019).
gastric cancer (14 papers, 2019 to 2025). A primary or metastatic malignant neoplasm involving the stomach. "HNRNPC was overexpressed in chemo-resistant gastric cancer (GC) cells and suggested as the prognostic biomarker for GC." (PMID 36536402, 2022). "Taken together, these results proved that LINC00924 facilitates gastric cancer peritoneal metastasis via hnRNPC-regulated alternative splicing of Mnk2 in vivo." (PMID 36418856, 2022). "Additionally, high expression level of HNRNPC contributed to poor survival of patients with gastric cancer receiving chemotherapy and resulted in chemoresistance." (PMID 35832652, 2022). "HNRNPC has been reported to have various functions, such as increasing differentiation in type II testicular germ cell tumors (GCTs), inducing cell death in ovarian cancer, promoting chemoresistance, and indicating OS in gastric cancer and facilitating the progression of colorectal cancer." (PMID 33134160, 2020). "In addition, a high expression of HNRNPC has a poor prognosis and may act as a candidate biomarker for chemoresistance in gastric cancer." (PMID 32903675, 2020). "Moreover, HNRNPC has been identified as a candidate biomarker in gastric cancer chemoresistance." (PMID 31632489, 2019). "The results indicated that high expression of FTO (HR = 1.15, 95% CI = 1.02–1.29), HNRNPC (HR = 1.09, 95% CI = 1.02–1.18), YTHDC2 (HR = 1.22, 95% CI = 1.07–1.42), and WTAP (HR = 1.18, 95% CI = 1.02–1.33) have a worse survival in patients with gastric cancer." (PMID 31681576, 2019).
hepatocellular carcinoma (13 papers, 2011 to 2025). A malignant tumor that arises from hepatocytes. "These experimental results underscore the critical role of HNRNPC in the progression of hepatocellular carcinoma and highlight its potential as a therapeutic target for liver cancer, particularly as a target for immunotherapy." (PMID 39735682, 2025). "In the context of hepatocellular carcinoma (HCC), our analysis identified HNRNPC as an independent prognostic marker, with meaningful correlations observed between HNRNPC expression and various pathways implicated in tumor progression." (PMID 39735682, 2025). "To verify the interaction between CEBPA-DT and hnRNPC, we determined the subcellular location of hnRNPC; the results revealed that the hnRNPC mainly existed in the nucleus of hepatoma cells, consistent with the subcellular location of CEBPA-DT." (PMID 36471363, 2022). "Having established that S-HDAg and hnRNPC interact in the yeast two-hybrid assay, we decided to investigate if the two proteins also interact in vitro and in vivo in human hepatoma cells." (PMID 21774814, 2011). "Taken together, these data suggesting that CEBPA-DT may physically bind hnRNPC and induce the translocalization of hnRNPC from the nucleus to the cytoplasm of hepatoma cells." (PMID 36471363, 2022). "Having established that S-HDAg and hnRNPC interact in vitro, we next decided to investigate if both proteins also interact in vivo in the human hepatoma cell line Huh7-D12 which is stably transfected with HDV cDNA and constitutively expresses virus RNAs and antigens." (PMID 21774814, 2011). "Mechanismly, CEBPA-DT could bind with hnRNPC and induce the interaction between hnRNPC and DDR2 mRNA, reducing the DDR2 mRNA degradation and further promoting metastasis of hepatoma cells." (PMID 36471363, 2022). "To further clarify the mechanism of the interaction between hnRNPC and CEBPA-DT, we measured the expression levels of hnRNPC in CEBPA-DT control and overexpressing hepatoma cells; we observed that upregulation of CEBPA-DT did not alter the mRNA and protein levels of hnRNPC." (PMID 36471363, 2022).
lung adenocarcinoma (12 papers, 2020 to 2025). A carcinoma that arises from the lung and is characterized by the presence of malignant glandular epithelial cells. "The risk score for each lung adenocarcinoma patient would be calculated with the following formula: risk score = 0.0335 ∗ KIAA1429 + 0.0628 ∗ RBM15 + 0.0106 ∗ HNRNPC." (PMID 33193582, 2020). "In conclusion, the prognostic signature-based risk score calculated according to the expression levels of KIAA1429, RBM15, and HNRNPC, was not only strongly associated with clinical outcomes and clinicopathological features, but also an independent prognostic factor in lung adenocarcinoma." (PMID 33193582, 2020). "In addition, the prognostic signature-based risk score built according to the expression levels of KIAA1429, RBM15, and HNRNPC, was not only strongly associated with clinical outcomes and clinicopathological features, but also an independent prognostic factor in lung adenocarcinoma." (PMID 33193582, 2020). "Guo and colleagues also showed that HNRNPC was highly expressed in lung adenocarcinoma (LUAD) tissues and significantly related to smoking history, lymph node metastasis, and poor prognosis." (PMID 35502201, 2022). "In UALCAN and GEPIA databases, the data showed that the expression of HNRNPC was elevated in lung adenocarcinoma (LUAD) and lung squamous cell carcinoma (LUSC) tissues." (PMID 36536402, 2022). "High HNRNPC mRNA and protein expression is significantly related to poor overall survival in patients with lung adenocarcinoma." (PMID 34299277, 2021). "For instance, in lung adenocarcinoma, high HNRNPC and IGF2BP3 levels correlate with reduced overall survival, and a six-gene risk signature (KIAA1429, ALKBH5, METTL3, HNRNPC, YTHDC2, and YTHDF1) strongly correlated with various clinical and pathological features." (PMID 36831575, 2023). "Among these genes, KIAA1429, HNRNPC, YTHDC2, METTL3, WTAP, YTHDC1, and FTO were down expressed in lung adenocarcinoma, RBM15, ZC3H13, YTHDF1, YTHDF2, and ALKBH5 were up expressed." (PMID 32398949, 2020).
colon cancer (11 papers, 2017 to 2025). "We thus not only present evidence that APA can make a critical contribution to colon cancer progression but also provide an underlying molecular mechanism by identifying deregulation of hnRNPC expression as a critical novel regulator of cancer specific APA for a subset of genes." (PMID 31147722, 2019). "HNRNPC increased the phosphorylation of S220, which was detected in various cancers, including ovarian cancer and colon cancer." (PMID 35344508, 2022). "It is reported that YTHDF1 and HNRNPC can be used as prognostic factors for colon cancer and have potential value for colon cancer treatment." (PMID 32974160, 2020). "We found that elevated levels of hnRNPC in metastatic-derived colon cancer cells are responsible for driving CR- and UTR-APA of a subset of genes including MTHFD1L, which has been strongly linked to cancer progression." (PMID 31147722, 2019). "We identify that overexpression of hnRNPC has a critical role in the establishment of APA profiles characteristic for metastatic colon cancer cells, by regulating poly(A) site selection in a subset of genes that have been implicated in cancer progression including MTHFD1L." (PMID 31147722, 2019). "Fischl and colleagues reported that hnRNPC overexpression establishes specific alternative cleavage and polyadenylation (APA) profiles in metastatic colon cancer cells by regulating poly(A) site selection in cancer-implicated genes like MTHFD1L." (PMID 41429980, 2025). "It was previously reported that hnRNPC regulated cancer-specific alternative cleavage and polyadenylation (APA) profiles in colon cancer, which has a critical role in cancer progression." (PMID 34344861, 2021).